NDUFS3 (NADH:ubiquinone oxidoreductase core subunit S3)
Diseases named in the same sentence as NDUFS3 in open-access papers (continued):
Sharing a sentence is not in itself a finding about the gene and the disease.
melanoma (continued). "Following treatment with the AMPK inhibitor, NDUFS3-knockdown melanoma cells exhibited increased cell proliferation, possibly due to the downregulation of p-AMPK(T172) expression and the increase in PRPS1 activity." (PMID 40404919, 2025). "The AMPK activator AIACR (10 mM) inhibited the ability of NDUFS3 to promote the proliferation of melanoma cells." (PMID 40404919, 2025). "The results indicated that NDUFS3-overexpressing melanoma cells exhibited an increase in the NADPH/NADP+ ratio." (PMID 40404919, 2025). "Taken together, the results of the present study indicated that NDUFS3 promoted melanoma cell proliferation by upregulating the de novo synthesis of purine nucleotides." (PMID 40404919, 2025). "Our results indicated that NDUFS3 levels in the tumors were positively correlated with the melanoma tumor volumes in each group." (PMID 40404919, 2025). "We also found that in melanoma cells overexpressing NDUFS3, the levels of AMP, GMP, ADP, GDP, ATP, and GTP significantly increased." (PMID 40404919, 2025). "However, after the overexpression of NDUFS3, the PK enzyme activity in melanoma cells is also stronger than that in the control cells." (PMID 40404919, 2025). "A melanoma tissue microarray was used to detect NDUFS3 levels by immunohistochemistry (IHC)." (PMID 40404919, 2025). "The exact mechanism by which NDUFS3-induced alterations in OXPHOS affect glucose metabolism in melanoma cells remains unknown." (PMID 40404919, 2025). "However, the levels of key enzymes involved in purine nucleotide metabolism were increased in NDUFS3-overexpressing melanoma cells." (PMID 40404919, 2025). "In contrast, NDUFS3-knockdown melanoma cells showed opposite trends." (PMID 40404919, 2025). "Therefore, we investigated the effects of NDUFS3 on mitochondrial morphology and dynamics in melanoma cells." (PMID 40404919, 2025). "In addition, we identified that high OXPHOS activity is dependent on the NDUFS3-AMPK axis in melanoma." (PMID 40404919, 2025). "Interestingly, increased p-AMPK(T172) was observed in NDUFS3-knockdown cells, whereas p-AMPK(T172) was decreased in NDUFS3-overexpressing melanoma cells." (PMID 40404919, 2025). "The results of the present study further demonstrated that NDUFS3 could be used as a marker molecule of high OXPHOS activity in melanoma." (PMID 40404919, 2025). "Additionally, NDUFS3 overexpression in melanoma cells leads to increased Mfn2 and decreased DRP1, with the opposite effects observed upon NDUFS3 knockdown." (PMID 40404919, 2025). "Melanoma cells overexpressing NDUFS3 were incubated with an AMPK activator, leading to cell growth inhibition, which may be due to increased p-AMPK(T172) expression and decreased PRPS1 activity." (PMID 40404919, 2025). "Our study highlighted an unrecognized role for NDUFS3 in melanoma, which might be used as a potential therapeutic target for the treatment of this type of cancer." (PMID 40404919, 2025). "We found NDUFS3 were abnormally elevated in human melanoma and promoted melanoma proliferation." (PMID 40404919, 2025). "However, the role of NDUFS3 in human melanoma development is unclear." (PMID 40404919, 2025). "However, NDUFS3-knockdown melanoma cells exhibited reduced mitochondrial complexity." (PMID 40404919, 2025). "In addition, Flow cytometry and western blot analyses confirmed that NDUFS3 can regulate the expression of cell cycle proteins in melanoma cells, increase the proportion of cells in the S phase, accelerate cell division, and thus promote the proliferation of melanoma cells." (PMID 40404919, 2025). "Moreover, RT‒PCR analysis revealed that the abundance of key enzymes involved in purine nucleotide metabolism, such as adenyl succinate lyase (ADSL), IMP dehydrogenase 1/2 (IMPD1/2), and GMP synthase (GMPS), was significantly decreased in NDUFS3-knockdown melanoma cells." (PMID 40404919, 2025).
melanoma (continued). "Therefore, we speculated that NDUFS3 may affect the proliferation of melanoma cells through AMPK phosphorylated PRPS1 mediated nucleotide metabolism." (PMID 40404919, 2025). "Here, we confirmed that NDUFS3 plays a key role in regulating glucose metabolism, OXPHOS, and purine nucleotide metabolism in melanoma." (PMID 40404919, 2025). "The overexpression of NDUFS3 increases the OCR, CI enzyme activity and content in melanoma cells, while NDUFS3 knockdown decreases these parameters." (PMID 40404919, 2025). "As NDUFS3-mediated the metabolic changes of OXPHOS and glucose metabolism, melanoma cells produced more ATP, resulting in the inhibition of AMP kinase (AMPK)." (PMID 40404919, 2025). "Briefly, the NDUFS3-AMPK-PRPS1 signaling axis coupled OXPHOS, glucose metabolism, and purine nucleotide biosynthesis to regulate melanoma proliferation." (PMID 40404919, 2025). "LONP1 over-expression results in impaired complex I assembly in melanoma cells, upregulation of NDUFB6,8,10 and 11, and downregulation of NDUFV1, NDUFV2, NDUFS3 and NDUFS7." (PMID 38263327, 2024). "NDUFS3 activated the aerobic oxidation of glucose and OXPHOS and downregulated glycolysis, thereby promoting the production of greater amounts of ATP and inhibiting AMPK activity in melanoma." (PMID 40404919, 2025). "Moreover, we found that increased NDUFS3 abundance increased the complexity of the mitochondrial network and promoted OXPHOS in melanoma cells." (PMID 40404919, 2025). "Moreover, we have discovered for the first time that NDUFS3 acts as a ‘switch’ for the regulation of OXPHOS and glycolysis in melanoma." (PMID 40404919, 2025). "It is worth noting that our study has further confirmed that the abnormal expression of NDUFS3 primarily impacts the fluctuation of purine nucleotides in melanoma cells, as opposed to pyrimidine nucleotides." (PMID 40404919, 2025). "Although LC‒MS/MS results showed that knocking down NDUFS3 inhibited the TCA cycle in melanoma cells, it is worth noting that in SK-MEL-110 cells knocked down by NDUFS3, the content of five metabolites in the TCA cycle reaction from α-ketoglutarate to malic acid was upregulated." (PMID 40404919, 2025).
Obesity (2 papers, 2024). Accumulation of substantial excess body fat. "In the present study, we demonstrated that a Western-type diet can increase PFC mitochondrial respiratory complexes I (subunits NDUFS3 and NDUFA9) and II levels (FP) in a porcine model of obesity." (PMID 38397759, 2024).
sarcopenia (2 papers, 2022 to 2023). Progressive decline in muscle mass due to aging which results in decreased functional capacity of muscles. "Using this semi-quantitative method, the authors reported lower levels of the mitochondrial proteins ATP5A, NDUFS3, and SDHB in participants with frailty and sarcopenia." (PMID 36710345, 2023).
Sepsis (2 papers, 2025). Sepsis is defined as life-threatening organ dysfunction caused by a dysregulated host response to infection. "Lastly, the NDUFS3 gene, significantly expressed in the spleen of LOP, protects the kidneys from sepsis-induced acute kidney injury (SI-AKI) by inhibiting ferroptosis and mitochondrial damage via the activation of the AMPK pathway." (PMID 41007990, 2025). "The logistic regression algorithm identified 8 genes (VDAC1, HSPA8, SOD1, HSPA9, TXN, NDUFS3, HSP90AB1, SNCA), among which 6 genes were closely correlated with the onset of sepsis-induced ALI (p < 0.05)." (PMID 40694561, 2025).
Ataxia (1 paper, 2020). Ataxia refers to impaired coordination of voluntary muscle movement. "Four-month-old Ndufs3 nKO mice stopped grooming and showed kyphosis and ataxia." (PMID 33148885, 2020).
Cognitive impairment (1 paper, 2023). Abnormal cognition is characterized by deficits in thinking, reasoning, or remembering. "NDUFB11 and NDUFS3 were associated with necrosis, hyperplasia, inflammation, renal disease, weight loss, memory impairment, and cognitive impairment." (PMID 37642954, 2023). "The core genes NDUFB11 and NDUFS3 were found to be associated with necrosis, hyperplasia, inflammation, renal disease, weight loss, memory impairment, and cognitive impairment." (PMID 37642954, 2023).
COVID-19 (1 paper, 2026). A disease caused by infection with severe acute respiratory syndrome coronavirus 2. "Among the genes included in these pathways, we found NQO1, CAT, RETSAT, NDUFS3, and HSD3B7, which were all already found associated with COVID-19 severity from our gene-based burden test analysis." (PMID 41500120, 2026).
Encephalopathy (1 paper, 2024). Encephalopathy is a term that means brain disease, damage, or malfunction. "Early intervention with AAV-PHP.eB-driven gene replacement successfully prevented the onset of encephalopathy in neuronal-knockouts of critical oxidative phosphorylation genes (Ndufs3 or Cox10)." (PMID 39169163, 2024). "Ndufs3-nKO mice develop a severe encephalopathy and need to be sacrificed between 4.5 and 5 months of age." (PMID 39169163, 2024).
endothelial dysfunction (1 paper, 2023). In vascular diseases, endothelial dysfunction is a systemic pathological state of the endothelium (the inner lining of blood vessels) and can be broadly defined as an imbalance between vasodilating and vasoconstricting substances produced by (or acting on) the endothelium. "In addition, co-treatment with PA and NAC reduced endothelial dysfunction, including restoration of total antioxidant capacity, cell viability, NO levels, and eNOS, DRP1, MFN2, NDUFS3, and UQCRC1 protein levels, as well as inhibition of IL6 and CHOP mRNA levels." (PMID 37237885, 2023).
ischemia (1 paper, 2021). A hypoperfusion of the BLOOD through an organ or tissue caused by a PATHOLOGIC CONSTRICTION or obstruction of its BLOOD VESSELS, or an absence of BLOOD CIRCULATION. "The ischemia-induced reductions in protein levels of NDUFA9 and NDUFS3 were prevented by GTT treatment." (PMID 34884479, 2021). "Decreases in the activity of complex I in vehicle-treated mice subjected to ischemia were accompanied by reductions in the protein levels of subunits NDUFA9 (to 78% of sham) and NDUFS3 (to 82% of sham), but not NDUFB6." (PMID 34884479, 2021).
male infertility (1 paper, 2018). The inability of the male to effect fertilization of an ovum after a specified period of unprotected intercourse. "This study suggests that downregulation of DJ-1 and NDUFS3 expression likely contributes to mitochondrial dysfunction, which may underlie AS pathogenesis, since current treatments for AS involve in vitro fertilization techniques rather than treatment of male infertility." (PMID 29849492, 2018).
Mitochondrial encephalopathy (1 paper, 2020). "Altogether, our results show that the ablation of NDUFS3 in CaMKIIa-expressing neurons induced a mitochondrial encephalopathy characterized by massive astrocyte activation in all brain regions analyzed and neuronal cell death localized to the hippocampus at 4 months of age." (PMID 33148885, 2020). "To investigate whether metformin can be used as an effective strategy to ameliorate a mitochondrial encephalopathy, we administered metformin to the neuron-specific Ndufs3 conditional KO mice (Ndufs3 nKO) mice and assessed its effects in the onset and progression of disease." (PMID 33148885, 2020).
myocardial infarction (1 paper, 2024). Gross necrosis of the myocardium, as a result of interruption of the blood supply to the area, as in coronary thrombosis. "Our study identified key genes (Aco2, Atp5a1, Ndufs3, and Ndufv1) associated with mitochondrial function in myocardial infarction." (PMID 39775580, 2024). "Ventricular expression of 10 central MitoDEGs (Aco2, Atp5a1, Ndufs3, Ndufv1, Cyc1, Suclg1, Sdha, Sdhb, Cs, and Ndufs2) was verified in a mouse model of myocardial infarction using PCR." (PMID 39775580, 2024). "Besides this, a total of 4 key genes were identified, Aco2, Atp5a1, Ndufs3 and Ndufv1, which were consistent with the expression trend of the mouse myocardial infarction model we constructed." (PMID 39775580, 2024).
renal cell carcinoma (1 paper, 2013). "In addition, decreased expression levels of GRIM-19 and NDUFS3 were found in renal cell carcinomas samples by western blot and RT-PCR analysis." (PMID 23630608, 2013).
thyroid cancer (1 paper, 2025). "Key metabolic regulators such as IDH1, PGAM1, NDUFS3, and LDHB were identified among these common genes, suggesting their central role in thyroid cancer metabolism." (PMID 40861812, 2025).
tumor (11 papers, 2013 to 2025). "Compared with those in control cells, the p-AMPK(T172)/AMPK ratio in tumor tissues overexpressing NDUFS3 was reduced, while the p-AMPK(T172)/AMPK ratio in tumor tissues with NDUFS3 knockdown was increased." (PMID 40404919, 2025). "This was confirmed in a recent proof of concept study in 2 different tumor backgrounds (HCT116 and 143B) having a nuclear-encoded NDUFS3 knock-out, where HIF-1α stabilization was abolished, but that tumors were able to re-adapt to the hypoxia response." (PMID 32509579, 2020). "The expression levels of NDUFS3 are heterogeneous in different tumor types." (PMID 40404919, 2025). "We further compared the expression of NDUFS3 in the tumor tissues of each group." (PMID 40404919, 2025). "This may be a self-compensatory mechanism of tumor cells supplementing α-ketoglutarate with glutamine, aimed at compensating for the reduced ATP production caused by mitochondrial OXPHOS dysfunction caused by knocking down NDUFS3." (PMID 40404919, 2025). "Further analysis by qPCR and Western blot of NDUFS3 (complex I) and ATP5a (complex V) showed reduced mRNA and protein levels in MMTV-Neu/KO tumours." (PMID 36933062, 2023). "To further bolster our conclusions, we examined tumor growth of A549 cells expressing NDI1 and shRNA targeting mammalian NDUFS3, a subunit of the human mitochondrial complex I." (PMID 24843020, 2014). "Network 3 was characterised by the insertion of a hub protein HNF4alpha, a transcription factor recently shown to play a role in other neoplasias and Network 4 was characterised by numerous mitochondrial-localised proteins (CAT, IDH3A, NDUFS3 and other complex 1 proteins, OXCT1 and PRDX3)." (PMID 24838487, 2014). "Furthermore, Dox-treated masses displayed ultrastructural mitochondrial alterations and lack of necrosis at tumor leading margins, a phenotype resembling NDUFS3 knockout xenografts." (PMID 30796225, 2019). "In fact, of all protein subunits with significant differences in abundance between tumor and nontumor, only 4 were significantly upregulated in DEN-T: Ndufa13, Ndufs3, Ndufs8, and Ndufv2." (PMID 35756609, 2022).
cancer (10 papers, 2013 to 2025). A tumor composed of atypical neoplastic, often pleomorphic cells that invade other tissues. "and NDUFS3, which is indirectly linked to cellular energetics, often dysregulated in cancer." (PMID 32295075, 2020). "Among these, NDUFV2 and its closely related family member NDUFS3 highlight the potential involvement of mitochondrial dysfunction in cancer pathophysiology." (PMID 40861812, 2025). "There are various studies on the evaluation of the role of NDUFS3 as a part of CxI in different cancers." (PMID 37482618, 2023). "In this study, we separately inhibit mitochondrial complex I activity by suppressing its two subunits, GRIM-19 and NDUFS3, using siRNA technique and determine the role of complex I in cancer metastasis." (PMID 23630608, 2013). "Further, in syngeneic CI-competent cancer models (NDUFS3+/+) we found that metformin treatment induces apoptosis at concentrations at which CI is not fully inhibited, indicating that the antiproliferative effects of this drug result also from the inhibition of other targets." (PMID 36349549, 2022). "In order to determine if mitochondrial complex I has a role in metastasis-related cancer behavior, two subunits of complex I, GRIM-19 or NDUFS3, were separately knocked down using siRNA in Hela cells." (PMID 23630608, 2013). "To investigate the specificity of three CI targeting compounds, namely metformin, EVP 4593 and BAY 87-2243, we exploited unique cancer cell models lacking CI previously generated by knocking out the core subunit gene NDUFS3." (PMID 36349549, 2022).
myopathy (7 papers, 2020 to 2023). A disease of the muscle in which the muscle fibers do not function properly. "The proteins such as NDUFS3 identified by the GCN link prediction methods are important for reversion of myopathies in mice." (PMID 35328027, 2022). "Restored NDUFS3 levels in mouse skeletal muscle has equally led to myopathy reversion via mitochondrial complex I regeneration." (PMID 35788655, 2022). "Mice with Ndufs3 knocked out in skeletal muscle (Ndufs3-smKO) experience progressive myopathy characterized by a decline in motor coordination and overall activity." (PMID 35668433, 2022). "rAAV9‐Ndufs3 delivered systemically into 15‐ to 18‐day‐old mice effectively restored NDUFS3 levels in skeletal muscle, precluding the development of the myopathy." (PMID 31916679, 2020). "The remarkable rescue of NDUFS3 protein expression levels and activity correlates with the myopathy improvement." (PMID 31916679, 2020). "Deletion of NDUFS3 gene in muscle would induce myopathy phenotype in mice." (PMID 37165455, 2023). "NDUFS3 protein levels were undetectable in muscle of 15‐day‐old smKO mice, and myopathy symptoms could be detected by 2 months of age, worsening over time." (PMID 31916679, 2020). "The conditional absence of NDUFS3 in the skeletal muscle of our CI‐deficient mouse model resulted in the development of a progressive myopathy that reduced lifespan to approximately 6–8 months." (PMID 31916679, 2020). "Curiously, unlike LS patients and Ndufs4-KO and Ndufs3-smKO mice, Surf1 knockout (KO) mice do not develop neurodegeneration or myopathy." (PMID 35668433, 2022). "We have recently described the Ndufs3 smKO model, a conditional KO mouse lacking the NDUFS3 subunit exclusively in skeletal muscle that develops a progressive myopathy and has a reduced life span." (PMID 33148885, 2020).
mitochondrial disease (1 paper, 2025). "NADH-ubiquinone oxidoreductase (NDUFS3) has been associated with mitochondrial disease and muscle degeneration, but knockout Ndufs3 mice had increased central nuclei in their muscle fibers and did not have the same physical characteristics as identified in the dozer lambs." (PMID 39858630, 2025).
NDUFS3 also shares sentences with these, for which no sentence is quoted: glaucoma (3 papers); Huntington disease (3); mitochondrial neurogastrointestinal encephalomyopathy (3); invasive breast carcinoma (2); Leber hereditary optic neuropathy (2); lung adenocarcinoma (2); neurodegenerative disease (2); schizophrenia (2); serous ovarian adenocarcinoma (2); sleep disorder (2); acute kidney injury (1); acute myocardial infarction (1); Asthenozoospermia (1); asthma (1); Barth syndrome (1); brain diseases (1); brain tumor (1); cardiomyopathy (1); chromophobe renal cell carcinoma (1); Cockayne syndrome (1); colon cancer (1); Friedreich ataxia (1); glioblastoma (1); hypertrophic cardiomyopathy (1); infection (1); insomnia (1); invasive ductal carcinoma (1); kidney cancer (1); lactic acidosis (1); lung carcinoma (1).
A further 13 diseases each share a sentence with NDUFS3 in 1 paper.